CCDC144NL-AS1 (CCDC144NL antisense RNA 1)
Synonyms: LOC339260
Gene: Long non-coding RNA gene on chromosome 17 (20,841,125 to 21,002,324, forward strand). Ensembl gene ENSG00000233098.
Diseases named in the same sentence as CCDC144NL-AS1 in open-access papers:
CCDC144NL-AS1 is named in the same sentence as 1 disease in open-access papers, as found by Europe PMC text mining. Sharing a sentence is not in itself a finding about the gene and the disease. The quoted sentences say what the papers report.
gastric cancer (1 paper, 2021). A primary or metastatic malignant neoplasm involving the stomach. "The survival analysis showed that high expression of CCDC144NL antisense RNA 1 (CCDC144NL-AS1) and LINC01614 was positively correlated with the poor prognosis of patients with gastric cancer." (PMID 35083139, 2021).